SERPINF1 (serpin family F member 1)
Diseases named in the same sentence as SERPINF1 in open-access papers (continued):
Sharing a sentence is not in itself a finding about the gene and the disease.
bladder tumor (2 papers, 2022 to 2023). "We compared the mRNA expression of CDH11, COL6A3, EDNRA, and SERPINF1 between bladder tumor and neighboring healthy tissues, respectively." (PMID 36595851, 2022).
Cervical tumor (2 papers, 2016 to 2017). "TXNDC5 contributes to the process of vasculogenic mimicry, cell migration and cell proliferation of cervical tumors by down-regulating SERPINF1 and TRAF1 expression." (PMID 29207620, 2017).
COVID-19 (2 papers, 2022 to 2023). A disease caused by infection with severe acute respiratory syndrome coronavirus 2. "It is conceivable that the increased activity of SERPINF1 and THBS2 together with the high activity of HIF1A contribute to favoring of intussusceptive angiogenesis over conventional sprouting angiogenesis in the hypoxic environment of COVID-19 pulmonary involvement." (PMID 35163504, 2022).
otosclerosis (2 papers, 2016 to 2024). Formation of spongy bone in the labyrinth capsule which can progress toward the stapes (stapedial fixation) or anteriorly toward the cochlea leading to conductive, sensorineural, or mixed hearing loss. "Five additional mutations were identified in six individuals across a cohort containing 84 unrelated individuals with a family history of otosclerosis meaning that 8.0% of familial otosclerosis patients had a rare SERPINF1 mutation." (PMID 27056980, 2016). "Five additional rare variants were identified in SERPINF1 from a cohort of 84 familial cases of otosclerosis." (PMID 27056980, 2016). "We analysed the effect of these mutations and identified SERPINF1 as the first disease-causing gene in otosclerosis." (PMID 27056980, 2016). "Allele frequencies of the SERPINF1 variants identified were much greater in the unrelated otosclerosis cohort compared with their reported frequencies in the variant databases, 1000 Genomes and NHLBI Exome Sequencing Project." (PMID 27056980, 2016). "Six rare heterozygous SERPINF1 variants were found in seven patients in our familial otosclerosis cohort; three are missense mutations predicted to be deleterious to protein function." (PMID 27056980, 2016). "Further sequencing of all coding exons and intron–exon junctions in SERPINF1 in the otosclerosis cohort revealed three additional rare non-synonymous mutations in exon 3 and exon 4 of SERPINF1 (c.167C > G, c.331G > A, c.392C > A)." (PMID 27056980, 2016). "To determine whether the mutations in SERPINF1-012 5′-UTR may play a role in otosclerosis, we examined the read counts for each SERPINF1 exon in the RNA-seq data from stapes bone to assess alternatively spliced isoform expression." (PMID 27056980, 2016). "The identification of SERPINF1 mutations in patients with familial otosclerosis in this study and the altered stapes expression observed in the gene that encodes PEDF provide a new link between heparan sulphate and modulation of TGFβ signalling in otosclerosis." (PMID 27056980, 2016). "Exon 5 of SERPINF1 was subsequently sequenced in a further 31 unrelated individuals with a family history of otosclerosis identifying a novel 3 bp deletion (c.440-40_440-38delTCG) in one individual." (PMID 27056980, 2016). "The most surprising observation in our study is that SERPINF1-012 expression is also reduced in stapes from a heterogeneous cohort of 75 unrelated otosclerosis patients." (PMID 27056980, 2016). "Therefore, given SERPINF1’s known role in bone regulation these data suggest SERPINF1 is an excellent candidate for an otosclerosis gene." (PMID 27056980, 2016). "In addition, we found that the level of SERPINF1 mRNA is significantly reduced in the general otosclerosis sample for both assays compared with controls." (PMID 27056980, 2016). "While the SERPINF1 gene was found to lack sufficient evidence in relation to the etiology of otosclerosis, a recent publication has suggested that a variant of SMARCA4 might be the cause of otosclerosis." (PMID 38327547, 2024). "Importantly, all of the otosclerosis patients with SERPINF1 mutations display no OI and have not reported a disproportionate amount of broken bones." (PMID 27056980, 2016). "Furthermore, RT-qPCR analysis of stapes bone cDNA showed that SERPINF1-012 expression is reduced in otosclerosis patients with and without SERPINF1 mutations, suggesting that it may be a common pathogenic pathway in the disease." (PMID 27056980, 2016).
scoliosis (2 papers, 2020 to 2022). A congenital or acquired spinal deformity characterized by lateral curvature of the spine. "In particularly, OI patients with the novel variant c.907C > T in SERPINF1 presented the most severe phenotypes: with 45–100 times of fractures, severe scoliosis and extremely short stature (Z-score < −8)." (PMID 33093841, 2020).
triple-negative breast carcinoma (2 papers, 2023 to 2025). An invasive breast carcinoma which is negative for expression of estrogen receptor (ER), progesterone receptor (PR), and human epidermal growth factor receptor 2 (HER2). "SERPINF1 was found to be anti-angiogenic and prevents new blood vessels from forming in triple-negative breast cancer." (PMID 40600125, 2025).
Bruck syndrome (1 paper, 2025). Bruck syndrome is characterized by the association of osteogenesis imperfecta and congenital joint contractures. "Three patients were identified with mutations in the P3H1, LEPRE, CRTAP, SERPINF1, PLOD2 (Bruck syndrome), TGFB1, and SGMS2 genes (Calvarial Doughnut Lesions with Bone Fragility)." (PMID 39941180, 2025).
diabetic neuropathy (1 paper, 2017). A chronic, pathological complication associated with diabetes mellitus, where nerve damages are incurred due to diabetic microvascular injury involving small blood vessels that supply these nerves, resulting in peripheral and/or autonomic nerve dysfunction. "In diabetic neuropathy, 31 genes were studied in a single year, for example, HMGB1, IGFBP5 and SERPINF1 (PEDF)." (PMID 28761062, 2017).
intrahepatic cholangiocarcinoma (1 paper, 2022). A carcinoma that arises from the intrahepatic bile duct epithelium in any site of the intrahepatic biliary tree. "Together with THBS1 and SERPINF1, it has also been shown to inhibit angiogenesis in patients with intrahepatic cholangiocarcinoma." (PMID 35163504, 2022).
Left ventricular diastolic dysfunction (1 paper, 2022). Abnormal function of the left ventricule during left ventricular relaxation and filling. "SERPINF1 strongly inhibits angiogenesis, and SERPINF2 is involved in alpha-2-plasmin inhibitor deficiency, vasculitis, and left ventricular diastolic dysfunction." (PMID 35990977, 2022).
ptosis (1 paper, 2020). The drooping of the upper eyelid. "Statistical analysis was conducted for WNT1, SERPINF1 and FKBP10, with > 3 probands, and only ptosis was significantly different between groups." (PMID 33093841, 2020).
spinal muscular atrophy (1 paper, 2023). A motor neuron disease that affect the muscles, and characterized by muscle weakness and atrophy resulting from progressive degeneration and irreversible loss of the anterior horn cells in the spinal cord (i.e., lower motor neurons) and the brain stem nuclei. "Thus, the previously observed downregulation of SERPINF1 was primary linked to the neuromuscular disturbances and spinal muscular atrophy in affected patients rather than to bone fragility." (PMID 37455927, 2023).
temporal lobe epilepsy (1 paper, 2024). A localization-related (focal) form of epilepsy characterized by recurrent seizures that arise from foci within the temporal lobe, most commonly from its mesial aspect. "Several apolipoproteins (APOA1, APOD, and APOA4), serpin protease inhibitors (SERPINA3, SERPINF1, etc.), complement components (C9, C8, and C1R), and a total of 42 proteins were found to be significantly upregulated in the temporal lobe epilepsy group." (PMID 39063177, 2024).
tumor (153 papers, 2008 to 2026). "Among them, MyCAFs (Col1al+ and SERPINF1+) had upregulated expression of extracellular matrix pathways and were associated with tumor cell proliferation, intraneural invasion, decreased survival, and higher tumor recurrence." (PMID 36980203, 2023). "From the TIMER web resource, the association between CDH11, COL6A3, EDNRA, and SERPINF1 immune signatures and tumor purity or numerous vital immune cells was revealed." (PMID 36595851, 2022). "It was noted that the expression of CDH11, COL6A3, EDNRA, and SERPINF1 were negatively associated with tumor purity." (PMID 36595851, 2022). "Interestingly, most of these genes have been implicated in general mechanisms of tumor biology, such as SERPINF1, reported as an inhibitor of angiogenesis and tumor suppressor, ASAP2, an EGFR pathway activator, or ELN and KRT8 related to the process of EMT." (PMID 34758873, 2021). "Concerning SERPINF1 gene, a suspected tumour suppressor gene, its forced expression induced a slower rate of cell proliferation, suggesting that a decrease of Serpinf1 may be associated with an increased cell proliferation." (PMID 23359294, 2013). "In vivo experiments revealed that SERPINF1 overexpression suppressed tumor growth in xenograft models." (PMID 41668508, 2026). "In GC tissue, in addition to the expression of fibroblasts, SERPINF1 was also expressed in tumor cells, suggesting a similar expression pattern of CPZ." (PMID 40296906, 2025). "SERPINF1 is a known antiangiogenic factor with many additional functions like anti-tumour, anti-inflammation, nutrition, and nerve protection functions, and is involved in fat metabolism." (PMID 37509322, 2023). "It is highly conceivable that SERPINF1 mediates the balance between the activation of tumor growth and the inhibition of tumor angiogenesis." (PMID 36980858, 2023). "In various cancers, including EC, the expression of SERPINF1 is lower in tumour tissue than in control tissue." (PMID 37509322, 2023). "In a group of patients with stages IB–IV EC (n = 11), TIMP2, CSF3, ENPP2, and SERPINF1 were significantly down-regulated in tumour tissue, by 4.9-fold, 9.6-fold, 10.2-fold, and 9.2-fold, respectively." (PMID 37509322, 2023). "Our IHC staining results on the GC tissue microarray demonstrated that SERPINF1 expression in GC tissues was obviously higher than that in adjacent non-tumor tissues (P<0.05)." (PMID 36505458, 2022). "Additionally, the upregulation of A2M and SERPINF1 suggested enhanced immune-modulatory and anti-angiogenic effects, potentially limiting tumour invasion and vascularisation." (PMID 40725093, 2025). "The expression of OSMR and LRP6 in tumor cells and SERPINF1 in stromal cells was detected by IHC." (PMID 37333017, 2023). "Furthermore, SERPINF1-related pathways were investigated using single-cell RNA-sequencing (scRNA-seq) data from the Tumor Immune Single-cell Hub (TISCH) database." (PMID 36980858, 2023). "CDH11, COL6A3, EDNRA, and SERPINF1 were all negatively correlated with tumor purity." (PMID 36595851, 2022). "In addition, genes that were upregulated in tumor-derived iCAFs were associated with the regulation of the inflammatory response, namely, IL6ST, NFKBIA, NT5E, SERPINF1, and NFKBIZ, suggesting that they play roles in communicating with immune cells." (PMID 34976204, 2022). "Thus, downregulation of Serpinf1 in the context of α7HMZ livers is consistent with P2-HNF4α activation of the Wnt/β-catenin pathway and promoting tumor growth." (PMID 30341289, 2018). "Interestingly, SERPINF1 exhibits bidirectional regulatory effects in tumor development." (PMID 38918587, 2024). "We therefore examined whether expression of BRD4 and that of SERPINF1 is correlated in human OC specimens, with the use of a published database containing gene expression profiles for tumor specimens obtained by laser capture and microdissection from 53 patients with high-grade serous OC38." (PMID 36056141, 2022).
tumor (continued). "Serpin family F member 1 (SERPINF1), also known as pigment epithelium-derived factor (PEDF), is a multifunctional secreted protein that can exert an anti-tumor effect by inhibiting angiogenesis." (PMID 36980858, 2023). "On the basis of our data obtained from mice, we examined the relation between the expression of the PEDF gene (SERPINF1) and that of genes for macrophage markers in tumor specimens of OC patients in TCGA." (PMID 36056141, 2022). "A variety of tissues express the gene Serpinf1 for PEDF, which is altered in retinopathies and in tumor tissues as well." (PMID 34069505, 2021). "Also, SsGESA and ESIMATE were conducted to examine the relationship between the expression of SERPINF1 and TFPI2 with tumor microenvironment in GC." (PMID 36505458, 2022). "In details, the decrease of FGF2, FLT1, CCL2 mRNA, along with increase of SERPINF1 mRNA were observed in EP300 knockdown ESCC cells, predicting that EP300 may promote tumor initiation via angiogenesis in ESCC." (PMID 31632486, 2019).
cancer (92 papers, 2008 to 2026). A tumor composed of atypical neoplastic, often pleomorphic cells that invade other tissues. "Decreased levels of SERPINF1 are associated with angiogenesis, fibrosis, inflammation, autophagy, metastasis, and prognostic deterioration in tumors, and SERPINF1 plays a multifunctional role and has therapeutic potential in a variety of cancers." (PMID 37872487, 2023). "NRCAM promotes cellular growth and differentiation, SERPINF1 inhibits angiogenesis in the prostate, and complements are peptidases that aid in cancer development." (PMID 32764784, 2020). "It has also been reported that SERPINF1 is involved in various cancers." (PMID 36980858, 2023). "A comparison of the high-SERPINF1 versus the low-SERPINF1 cluster showed that cancer-promoting signaling pathways were significantly enriched, including for Notch signaling, E2F targets, mitotic spindle, G2M checkpoint, wnt/β-catenin signaling, and MYC target pathways." (PMID 36980858, 2023). "In addition, KEGG analysis at the single-cell level also demonstrated that cancer-promoting signaling pathways were enriched in the high-SERPINF1 cluster." (PMID 36980858, 2023). "ATRA-induced expression of the SERPINF1/Serpinf1 gene was reported in human retinal pigment epithelia and cancer cells, bovine retinal endothelial cells, mouse and rat neurons and neuron-derived cancer cells." (PMID 25881671, 2015). "Notably, SERPINF1 seems to have bidirectional functions in different cancers." (PMID 36980858, 2023). "Higher expression of SERPINF1 and TFPI2 was accompanied by lower cancer stemness while with a higher stromal score, immune score and ESTIMATE score." (PMID 36505458, 2022).
infection (12 papers, 2010 to 2025). The state of being infected such as from the introduction of a foreign agent such as serum, vaccine, antigenic substance or organism. "In our work, SERPINF1 is upregulated and has been previously suggested as a biomarker of prognosis for infection severity." (PMID 37628421, 2023). "The top 5 downregulated genes in the UB of CIE mice at 1 wk post-infection included Igf1, Col6a3, Myrf, Itga7, and Serpinf1." (PMID 36490282, 2022). "CD40 has been implicated in both P. aeruginosa and S. pneumoniae infection, while PEDF (SERPINF1) is known to inhibit angiogenesis and acts as a neurotrophic factor in neuronal differentiation." (PMID 24086587, 2013). "Moreover, the authors found that the antiviral effects of SERPINA1, SERPINE1, SERPINE2, and SERPINF1 were observed during the first steps of infection in HBEC ALI cultures, revealing reduced SARS-CoV-2 entry into target cells." (PMID 38601158, 2024).
bone disorder (2 papers, 2016 to 2021). "OI is a brittle bone disorder caused by mutations in COL1A1 or COL1A2 in over 90% of cases; with mutations in many other genes, including SERPINF1, responsible for the other 10% of cases." (PMID 27056980, 2016).
female reproductive diseases (2 papers, 2017 to 2024). "Albeit no specific roles have previously been postulated for SERPINF1 depending on the gender, it is noteworthy that the findings associated with gynaecological diseases are correlated to alterations in the control of physiological angiogenesis." (PMID 28273097, 2017).
neurodevelopmental disorder (1 paper, 2021). A behavioral and cognitive disorder with onset during the developmental period that involves impaired or aberrant development of intellectual, motor, or social functions. "Although the Serpinf1 gene is localized in the 17p13.3 chromosome region and often deleted or duplicated, resulting in neurodevelopmental disorders, few studies have taken into account the roles of Serpinf1 (PEDF) in brain development." (PMID 35053800, 2021).
SERPINF1 also shares sentences with these, for which no sentence is quoted: diabetic retinopathy (40 papers); retinopathy (23); type 2 diabetes (19); age-related macular degeneration (17); osteosarcoma (16); ischemia (15); glaucoma (13); diabetic nephropathy (11); proliferative diabetic retinopathy (10); cardiovascular diseases (9); chronic kidney disease (9); metabolic disorders (9); nasopharyngeal carcinoma (9); acute myocardial infarction (8); Hyperglycemia (8); Nephropathy (8); choroidal neovascularization (7); colorectal cancer (7); coronary artery disease (6); Hepatic steatosis (6); polycystic ovary syndrome (6); retinal ischemia (6); idiopathic pulmonary fibrosis (5); lymph node metastasis (5); myeloma (5); neurodegenerative disease (5); retinal diseases (5); rheumatoid arthritis (5); Alzheimer disease (4); breast tumour (4).
A further 185 diseases each share a sentence with SERPINF1 in 4 papers or fewer.